GAPDH (glyceraldehyde-3-phosphate dehydrogenase)
Diseases named in the same sentence as GAPDH in open-access papers (continued):
Sharing a sentence is not in itself a finding about the gene and the disease.
neuroblastoma (19 papers, 2009 to 2023). Neuroblastoma (NB) is the most common solid, extracranial childhood tumor. "The data presented in this article demonstrate that different fractions of pre-denatured GAPDH may cause apoptotic processes in neuroblastoma cells." (PMID 30225299, 2018). "If these competing roles can be selectively inhibited, GAPDH has potential as a therapeutic target in neuroblastoma, particularly in combining GAPDH glycolytic, autophagy or DNA repair inhibitors with standard chemotherapy." (PMID 36267982, 2022). "In cultured NG108-15 neuroblastoma-glioma hybrid cells, GAPDH inhibition for 24 hours efficiently induced apoptosis." (PMID 36267982, 2022). "This review will focus on the role of the GAPDH protein in metabolism, nutrient transport and survival in neuroblastoma." (PMID 36267982, 2022). "The plasma membrane localization of GAPDH and its role in glucose uptake have been verified in neuroblastoma." (PMID 36267982, 2022). "A subset of GAPDH has been identified at the plasma membrane, and we detected plasma membrane GAPDH in neuroblastoma cells by membrane labeling." (PMID 36267982, 2022). "Koningic acid was isolated from three different fungi from soil and inhibits GAPDH with resulting activity towards a variety of cancer cell types, including neuroblastoma." (PMID 36267982, 2022). "Other studies support a role for nuclear GAPDH in the progression of apoptosis due to multiple stimuli in neuroblastoma." (PMID 36267982, 2022). "First, there are numerous gene expression studies in neuroblastoma using GAPDH as a loading control for other genes, in spite of concerns over utilizing GAPDH as a loading control." (PMID 36267982, 2022). "Other proteins linked to metabolism such as eEF2, PFKP, GAPDH and ribosomal protein L10a were also confirmed to be enriched in the EVs secreted by MYCN-positive neuroblastoma cells." (PMID 34847775, 2021). "Recently, GAPDH was shown to be released from PC-12HttQ103 rat neuroblastoma cells in complex with long poly-Q chains." (PMID 34341704, 2021). "A robust amplification of GAPDH in the cDNA was prepared from the neuroblastoma cell line (i.e., SH-SY5Y cells) as a positive control." (PMID 31366968, 2019). "Another study described physical interaction of PREP with GAPDH, and suggested that this would modulate GAPDH translocation to the nucleus during apoptosis in neuroblastoma cells." (PMID 28261087, 2017). "In this study, SDHA, UBC and GAPDH housekeeping genes were used as endogenous controls based on previous data which showed these genes to be most stably expressed in human neuroblastoma cells." (PMID 19445671, 2009). "In neuroblastoma cells, GAPDH contributes to glucose uptake." (PMID 36267982, 2022). "One limitation to the use of GAPDH inhibitors for treating neuroblastoma is the possibility that some inhibitors that block GAPDH activity in glycolysis and glucose uptake may also inhibit apoptosis by suppressing a pro-apoptotic nuclear form of GAPDH." (PMID 36267982, 2022). "Membrane-associated GAPDH also participates in iron uptake, although this has not been tested in neuroblastoma." (PMID 36267982, 2022). "One of the key questions is how the different pathways directed by GAPDH might intersect in neuroblastoma." (PMID 36267982, 2022). "However, research in this area, including therapeutic development, is needed in order to advance GAPDH inhibitors as therapeutic approaches for neuroblastoma." (PMID 36267982, 2022). "Other studies directly addressed the function of GAPDH in neuroblastoma." (PMID 36267982, 2022). "This review will focus on three areas as they pertain to neuroblastoma: (i) the role of GAPDH in glycolysis, (ii) GAPDH functions in plasma membrane nutrient transport, and (iii) GAPDH nuclear functions as they pertain to DNA repair and the control of apoptosis and autophagy." (PMID 36267982, 2022). "To test whether GAPDH is released from cells affected by exogenous Aβ, we utilized a human neuroblastoma cell line, SH-SY5Y." (PMID 34341704, 2021).
neuroblastoma (continued). "However, it is unclear whether GAPDH-mediated iron uptake has any role in ferroptosis in neuroblastoma." (PMID 36267982, 2022). "To correlate the degree of memory deficit with GAPDH cytotoxicity, we obtained CSF from each group of rats and estimated its effect on SH-SY5Y neuroblastoma cell survival." (PMID 34341704, 2021). "Previous studies with qPCR have found HPRT1 and SDHA to show low expression variability in primary neuroblastoma and also, specifically for the SY5Y line, GAPDH, M-RIP, and POLR2F were found to be reliable genes to be used as normalization factors." (PMID 34066513, 2021). "We therefore applied these criteria to identify potential HK genes for SY5Y cells, also checking the expression of commonly used HK genes for qPCR normalization in neuroblastoma experiments involving cell lines, such as ACTB, B2M, and GAPDH." (PMID 34066513, 2021). "For 34 neuroblastoma samples, the proposed new algorithm yielded the smallest upper bound for the variance of the geometric mean of six genes, ACTB, B2M, GAPDH, HPRT1, TBP, and YWHAZ." (PMID 20470420, 2010). "Additionally, the neuronal differentiation of neuroblastoma cells was confirmed by Western blotting using antibodies against NSE, GFAP and GAPDH." (PMID 31712567, 2019). "We report in human brain and human SH-SY5Y neuroblastoma cell lines that DJ-1 predominantly forms high molecular weight (HMW) complexes that included RNA metabolism proteins hnRNPA1 and PABP1 and the glycolysis enzyme GAPDH." (PMID 29016861, 2017). "Conversely, GAPDH was detected on the surface of Neuro2A and B103 neuroblastoma cells, and extracellular GAPDH increased neurite outgrowth in cultured neurons, although its role in neuroblastoma growth and survival were not determined." (PMID 36267982, 2022). "RT-PCR analysis showed mRNA expression of GLP-1R and glyceraldehyde-3-phosphate dehydrogenase (GAPDH; a housekeeping gene used for confirmation of the proper reactions) in DRG neurons and IFRS1 cells, as well as NSC-34 cells and ND7/23 mouse neuroblastoma/rat embryonic DRG neuron hybrid cells." (PMID 33804063, 2021). "In order to determine if there is a correlation between MYCN and GAS5 expression levels in neuroblastoma, 15 neuroblastoma cell lines were screened (6 MYCN-amplified and 9 non-amplified) for both MYCN and GAS5 expression by qRT-PCR, normalized to GAPDH." (PMID 28035057, 2017).
Parkinson disease (19 papers, 2008 to 2024). A progressive degenerative disorder of the central nervous system characterized by loss of dopamine producing neurons in the substantia nigra and the presence of Lewy bodies in the substantia nigra and locus coeruleus. "The role of GAPDH in Parkinson’s disease has also caused wide attention." (PMID 32331439, 2020). "Special attention to the nuclear translocation of GAPDH was prompted by the relationship of this phenomenon to the development of neurodegenerative disorders—primarily Parkinson’s disease." (PMID 34827652, 2021). "Most of the works were related to the study of the NO-induced apoptosis mediated by GAPDH, as well as to the relationship between S-nitrosylation of GAPDH and the development of neurodegenerative diseases—primarily Parkinson’s disease." (PMID 34827652, 2021). "Several pieces of evidence show the involvement of GAPDH in the development of neurodegenerative disorders such as Alzheimer’s, Huntington’s, and Parkinson’s diseases, which are characterized by the accumulation of protein aggregates." (PMID 31027346, 2019). "There is strong evidence that GAPDH can interact with β-amyloid and huntingtin proteins to regulate their cytotoxicity, thus directly linking to several neurodegenerative disorders, such as Alzheimer’s, Huntington’s, and Parkinson’s diseases." (PMID 36450447, 2023). "In a therapeutic context, selegiline—a pharmacological agent employed in Parkinson's disease treatment—can inhibit the S‐nitrosylation of GAPDH, thereby precluding its interaction with Siah1 and constraining the nuclear translocation of the GAPDH‐Siah complex, thus limiting cellular apoptosis." (PMID 38034101, 2023). "Moreover, it was shown that that deprenyl (a drug that ameliorates the progression of Parkinson’s disease) and other structurally related propargylamines bind with GAPDH and increase neuronal survival by interfering with apoptosis signaling pathways." (PMID 34827652, 2021). "Anti-dementia protective drugs such as the cholinesterase inhibitors tacrine, donezepil, and selegiline, as well as selective monoamine oxidase B inhibitors, are widely used for the treatment of Parkinson’s disease, mainly relying on their ability to interact with the GAPDH apoptotic cascade." (PMID 32331439, 2020). "Interestingly, there is some evidence suggesting the involvement of GAPDH aggregation in Alzheimer's and Parkinson's diseases." (PMID 28167533, 2017). "In addition to GAPDH’s role in viral infection, it is a major suspect in several neurodegenerative diseases in humans, including Huntington’s, Parkinson’s, and Alzheimer’s diseases." (PMID 27303403, 2016). "Thus, GAPDH is a major suspect in neurodegenerative diseases, including Alzheimer’s, Parkinson’s, and Huntington’s diseases." (PMID 26606248, 2015). "Also in the frontal cortex of Lewy Body diseased patients and in T-lymphocytes of Parkinson’s patients under dopaminergic therapies the GAPDH levels were significantly different from those of controls." (PMID 25470616, 2014). "Notably, when compared to control subjects GAPDH oxidation was increased in Alzheimer and Parkinson patients; GAPDH was also affected in ALS mouse models." (PMID 22028962, 2012). "Accumulating evidence has demonstrated that the glyceraldehyde-3-phosphate dehydrogenase (GAPDH) is a part of Lewy body inclusions and involves the pathogenesis of Parkinson’s disease (PD)." (PMID 26258539, 2015). "GAPDH nucleocytoplasmic shuttling not only participates in these processes, but has also been connected to cancer and neurodegenerative disorders, such as ALS, Alzheimer, or Parkinson disease." (PMID 22028962, 2012). "In amygdala, the overall piRNAs-aligned pseudogenes ratio is not different in Parkinson’s disease, but some related pseudogene-aligned piRNAs, including HSP90, MTCO1, MTCO2, YWHAZ, GAPDH, and MTND were upregulated in the PD group." (PMID 35269612, 2022).
bladder cancer (17 papers, 2007 to 2025). "ANOVA indicated that ACTB and GAPDH were differentially expressed among the diagnostic groups such as bladder cancer stage and grade." (PMID 30214686, 2018). "UM-UC-9 and UM-UC-6 bladder cancer cells expressed moderate levels of ADAM15 protein when normalized to GAPDH loading controls." (PMID 26930657, 2016). "Accordingly, we have also found that GAPDH was among the least stable genes in the studied bladder cancer cells under hypoxia." (PMID 27835695, 2016). "The PSCA mRNA expression levels in bladder cancer and normal urothelium tissues were normalized using GAPDH mRNA." (PMID 25624885, 2015). "In bladder cancer, a study showed that GAPDH, G6PD and HMBS were significantly changed between malignant and nonmalignant tissues." (PMID 17640361, 2007). "Similarly, analysis of expression by RNA-seq in a cohort of 158 bladder cancer patients revealed that elevated expression of AURKB and PLK4 was associated with high-grade disease, in contrast to GAPDH, which was expressed similarly in both grades." (PMID 31142743, 2019). "ChIP assay specificity was controlled by qRT-PCR on GAPDH as a constitutively expressed gene and CTCFL as a developmentally regulated gene weakly expressed in bladder cancer cells." (PMID 33322422, 2020). "Bladder cancer marker candidates as well as reference genes (ACTB, GAPDH, ALDOB) were assayed by RT-qPCR in 254 urine samples including 173 bladder cancer patient urine samples." (PMID 30214686, 2018). "Accordingly, seven of the most commonly used reference genes (ACTB, GAPDH, HPRT, B2M, SDHA, TBP, and 18S) were amplified in the three bladder cancer cell lines exposed to normoxia and hypoxia." (PMID 27835695, 2016). "GAPDH upregulation by BCG, other than being part of the characteristics of innate immunity against bladder cancer, might reflect the expedited glycolytic pathway for the benefit of brain tissue." (PMID 40699791, 2025). "We firstly explored the relative expression level of CASC2 in bladder cancer tissues (n=72) compared with corresponding non-tumor tissues (n=72) by qRT-PCR, and normalized to GAPDH." (PMID 28199978, 2017). "We also found that the expression levels of exosomal lncRNA-UCA1 in the serum of bladder cancer patients were markedly higher than that in healthy control subjects, and the expression levels of exosomal lncRNA-UCA1 were normalized to ACTB (β-actin) or GAPDH." (PMID 28841829, 2017).
COVID-19 (17 papers, 2020 to 2025). A disease caused by infection with severe acute respiratory syndrome coronavirus 2. "The enrichment of the oxidoreductase activity GO term [GO:0016491] among the COVID-19 survived cohort included underlying genes such as quinone oxidoreductase, pyruvate dehydrogenase, glyceraldehyde-3-phosphate dehydrogenase, and glyceraldehyde-3-phosphate dehydrogenase." (PMID 36476670, 2022). "They demonstrated that neutrophils displayed a reduction in GAPDH activity in severe COVID-19 and that GAPDH inhibition promoted neutrophil extracellular trap formation." (PMID 41007733, 2025). "Using metabolomics, the authors demonstrate that neutrophils display a reduction in GAPDH activity in severe COVID-19 and that GAPDH inhibition promotes neutrophil extracellular trap formation." (PMID 37147288, 2023). "Metabolic changes in neutrophils from patients with severe COVID-19 were consistent with reduced activity of the glycolytic enzyme GAPDH." (PMID 37147288, 2023). "The ratio of dihydroxyacetone phosphate:1,3-bisphosphoglycerate (DHAP:BPG) increased in severe COVID-19 neutrophils, consistent with a reduction in GAPDH activity." (PMID 37147288, 2023). "Further, GAPDH, the most commonly used reference gene in COVID-19 studies, turned out to be the least suitable." (PMID 36377893, 2022). "Remarkably, neither of the two most popularly used internal control genes in COVID-19, i.e., GAPDH and β-ACTIN, showed expression consistency across the patients with various severities of disease." (PMID 36377893, 2022). "Studies have shown that, in throat swabs and sputum specimens of 4 cases of COVID-19, the housekeeping gene GAPDH of human cells showed a typical amplification signal curve." (PMID 35340244, 2022). "Using the site-13 viral primers and two human gene-specific primers (RNAP and GAPDH), we were able to amplify and recover sequencing reads for the majority of viral sites for both nasopharyngeal and saliva samples from the COVID-19-positive patients." (PMID 35410128, 2022). "On the other hand, normalization with GAPDH highlighted significant expression heterogeneity (2-fold to over 600-fold) across the spectrum of COVID-19 and CAM." (PMID 36377893, 2022). "Surprisingly, the most commonly used internal control gene in COVID-19 studies, i.e., GAPDH, showed significant variations within healthy subjects and also between healthy and COVID-19 subjects who had a moderate or severe infection or CAM." (PMID 36377893, 2022). "In addition, the activity of the glycolytic enzyme glyceraldehyde-3-phosphate dehydrogenase (GAPDH) is reduced in patients with severe COVID-19, which decreases glycolysis and increases the activity of the HMP shunt." (PMID 38139412, 2023). "To this end, we pooled 45 COVID-19-positive and 15 COVID-19-negative patient samples and again observed that DeepSARS could detect significantly higher ratios of viral to hRNA (GAPDH+RNAP) reads in the COVID-19 patient samples." (PMID 35410128, 2022). "Clustering and shared upregulation of glycolytic enzyme encoding genes GALM, GAPDH, GPI, and ALDOA together with HIF1A, and transcripts regulating exhaustion (TIGIT and LAG3) suggested that hypoxia/anaerobic axis is associated with impaired CD8+TM function in COVID-19 BALF." (PMID 37029220, 2023). "In a subset of 70 individuals stratified by COVID-19 status, we measured VDR, DEFA1-3, CCL20, and GAPDH expression by RT-qPCR." (PMID 40904798, 2025). "The gene expression of S100A9, GAPDH, and LY96 was increased in all data of severe COVID-19 patients." (PMID 38262689, 2024). "For viral infections including COVID-19, β-ACTIN, GAPDH, and 18S rRNA (18S) are popularly used as internal controls (4, 15, –, 18)." (PMID 36377893, 2022). "TNF, GAPDH, MAPK3, MAPK1, EGFR, CASP3, MAPK8, mTOR, IL-2, and MAPK14 are important targets for YQS in COVID-19 treatment." (PMID 35340244, 2022). "GAPDH and β-ACTIN are among the most widely used reference genes for qRT-PCR studies, including those of COVID-19." (PMID 36377893, 2022).
COVID-19 (continued). "Using the comparative delta-CT method, we observed that GAPDH and PGC-1α showed the highest standard deviations across COVID-19 and CAM cases as evident from the cumulative standard deviation data for individual genes." (PMID 36377893, 2022). "To determine how gene expression varies based on normalization with CypA and GAPDH, we looked at genes such as NRF2, IL-6, and IL-15, whose expression profiles based on RNA sequencing were previously reported in COVID-19 patients (30, –, 33)." (PMID 36377893, 2022). "In module 4, enhanced glycolysis (increased GAPDH and PGAM1 expression) in patients with mild COVID-19 mediated proinflammatory processes (such as S100 and TNF family) and the IFN-mediated antiviral response in macrophages." (PMID 33936072, 2021). "Between 26th February to 1st November 2022, 154 COVID-19 and 165 uninfected patients were included in this study respectively, with 2 uninfected patients subsequently rejected due to a negative GAPDH one-step real-time RT-qPCR." (PMID 36482706, 2023). "That upon normalization with GAPDH both IL-6 and NRF2 showed massive induction (>400-fold) in the case of patients with mild infection and in pre- and post-CAM patients reinforces the idea that GAPDH is not a suitable reference gene for the COVID-19 spectrum." (PMID 36377893, 2022). "The CD16+ monocytes in the mild COVID-19 group expressed higher levels of glycolysis-related genes (PGAM1 and GAPDH), a fatty acid-related gene (HACD4), and an arginine and proline metabolism-related gene (SAT2), as well as lower levels of a cysteine and methionine metabolism-related gene (AHCYL1)." (PMID 33936072, 2021). "In module 2, enhanced expression of glycolysis (GAPDH and TPI1) and IFN response (IFITM2, IFITM1, IFITM3, IFNGR2, and ISG20) genes in human COVID-19 patients, particularly severely ill patients, may promote the differentiation of unswitched memory B cells into plasmablasts." (PMID 33936072, 2021). "Normalization with GAPDH, however, could not accurately capture the heterogeneity of the COVID-19 spectrum and that of CAM patients, and a significantly higher induction of NRF2 (1.3- to 268-fold in asymptomatic, mild, and moderate groups) was observed in COVID-19 patients." (PMID 36377893, 2022).